Y_RNA (Y RNA )
Gene: Miscellaneous RNA gene on chromosome 1 (171,253,906 to 171,254,022, reverse strand). Ensembl gene ENSG00000206692.
Homologues: Orthologues: chimpanzee Y_RNA (99% identical), macaque Y_RNA (85% identical). Paralogues in human: Y_RNA (79% identical), Y_RNA (77% identical), Y_RNA (76% identical), RNY1 (75% identical), Y_RNA (75% identical), Y_RNA (74% identical), RNY1P11 (73% identical), RNY1P8 (73% identical), Y_RNA (73% identical), Y_RNA (72% identical), Y_RNA (71% identical), RNY1P10 (70% identical), and 88 more.